FRMD4B (FERM domain containing 4B)
Description:
Member of GRP1 signaling complexes that are acutely recruited to plasma membrane ruffles in response to insulin receptor signaling. May function as a scaffolding protein that regulates epithelial cell polarity by connecting ARF6 activation with the PAR3 complex. Plays a redundant role with FRMD4A in epithelial polarization.
Synonyms: GRSP1; KIAA1013; 6030440G05Rik
Tractability: PROTAC: UniProt records ubiquitination sites on it.
Gene: Protein-coding gene on chromosome 3 (69,168,782 to 69,542,583, reverse strand). Ensembl gene ENSG00000114541.
Subcellular location: Cytoplasm, cytoskeleton; Cell junction, tight junction; Cell junction, adherens junction
Subcellular location (Human Protein Atlas): Centriolar satellite; Golgi apparatus; Nucleoplasm
Gene Ontology:
Biological process: establishment of epithelial cell polarity
Cellular component: extracellular region; adherens junction; bicellular tight junction; cytoplasm; cytoskeleton; ruffle
Genetic constraint (gnomAD): Loss-of-function variants: 26 observed, 56.67 expected, observed/expected ratio (o/e) 0.46, 90% interval 0.34 to 0.64. The upper end of that interval is the gene's LOEUF score, 0.64, which puts it in group 2 of 6, group 1 being the genes least tolerant of losing a copy. Missense variants: 773 observed, 720.58 expected, observed/expected ratio (o/e) 1.07, 90% interval 1.01 to 1.14. Synonymous variants: 306 observed, 281.56 expected, observed/expected ratio (o/e) 1.09, 90% interval 0.99 to 1.2.
Homologues: Orthologues: macaque FRMD4B (99% identical), chimpanzee FRMD4B (96% identical), mouse Frmd4b (94% identical), dog FRMD4B (93% identical), rat Frmd4b (93% identical), pig FRMD4B (92% identical), guinea pig FRMD4B (92% identical), rabbit FRMD4B (92% identical), tropical clawed frog frmd4b (68% identical), zebrafish frmd4ba (50% identical), zebrafish frmd4bb (49% identical), Caenorhabditis elegans F07C6.4 (21% identical). Paralogues in human: FRMD4A (48% identical), MSN (14% identical), RDX (14% identical), EZR (14% identical), NF2 (14% identical), ERMN (5% identical).
Diseases named in the same sentence as FRMD4B in open-access papers:
FRMD4B is named in the same sentence as 21 diseases in open-access papers, as found by Europe PMC text mining. Sharing a sentence is not in itself a finding about the gene and the disease. The quoted sentences say what the papers report.
heart failure (3 papers, 2010 to 2020). Inability of the heart to pump blood at an adequate rate to meet tissue metabolic requirements. "The FRMD4B gene is part of the GRP1 signaling complex, thereby recruited in response to insulin receptor signaling, but genetic variants have also been associated with heart failure." (PMID 25071839, 2014).
Alzheimer disease (2 papers, 2025). A progressive, neurodegenerative disease characterized by loss of function and death of nerve cells in several areas of the brain leading to loss of cognitive function such as memory and language. "Interestingly, integrated whole-transcriptome and genomic methylation analyses have identified both Frmd4a and Frmd4b as candidate gene products involved in networks specific to late-onset Alzheimer’s disease." (PMID 41155374, 2025).
celiac disease (2 papers, 2014 to 2019). An autoimmune genetic disorder with an unknown pattern of inheritance that primarily affects the digestive tract. "This study replicated a previous suggestive association within FRMD4B (3p14.1), confirming it as a celiac disease locus." (PMID 24999842, 2014).
Retinal dysplasia (2 papers, 2024 to 2025). Abnormal growth and differentiation, structure and appearance of the retina present from birth. "FRMD4B encodes a poorly characterized scaffolding protein involved in processes including cytoskeletal dynamics and protection against retinal dysplasia in mice." (PMID 40162949, 2025).
Age-related cataract (1 paper, 2021). A type of cataract (opacification of the lens) that forms during the course of aging. "Some of these genes associated with age-related cataracts include FRMD4B, NAALADL2, LOC105377670, LINC00968, LOC101929415, CTNNA3, LOC107984170, PRCP, and ZNF423, whereas others with a reduced risk include CFAP74, ACSL1, LOC101927668, LOC105369844." (PMID 34299682, 2021).
cerebellar ataxia (1 paper, 2023). A neurological syndrome characterized by clumsy and uncoordinated movement of the limbs, trunk, and cranial muscles. "In addition, mRNAs, such as cyclin dependent kinase inhibitor 2B (CDKN2B) is associated with cell growth and death, and FERM domain containing 4B (FRMD4B) is associated with corpus callosum agenesis with facial anomalies and cerebellar ataxia." (PMID 37663277, 2023).
cervical carcinoma (1 paper, 2020). A carcinoma arising from either the exocervical squamous epithelium or the endocervical glandular epithelium. "Notably, knockdown of FRMD4B by siRNA has been reported to induce significant resistance to thiopurine in U251 (human glioma) and Hela (human cervical carcinoma) cell lines." (PMID 33002292, 2020).
melanoma (1 paper, 2023). A malignant, usually aggressive tumor composed of atypical, neoplastic melanocytes. "For instance, MEF2A, EMP2, ZNF440, PIGL, FRMD4B, and HIF3A are not only downregulated in TCGA-SKCM melanoma samples but also essential for restraining tumor growth in CRIPSR KO screens." (PMID 37904237, 2023).
cancer (1 paper, 2018). A tumor composed of atypical neoplastic, often pleomorphic cells that invade other tissues. "The two mechanisms defined are intrinsically related to the pathogenesis of IBD, and likely will apply as general rules for the CUPID domains of FRMD4A, FRMD4B, and CCDC120 - proteins implicated in neurite outgrowth, and in human cancer, Alzheimer’s, celiac, and heart disease." (PMID 30355448, 2018).
neurodegenerative disease (1 paper, 2025). A disorder of the central nervous system characterized by gradual and progressive loss of neural tissue and neurologic function. "Moreover, understanding how loss-of-function in Frmd4a or Frmd4b contributes to related neurodegenerative diseases, potentially due to disrupted neuronal tissue homeostasis, is of significant importance." (PMID 41155374, 2025).
neurological diseases (1 paper, 2020). "These loci implicate genes highly expressed in brain and previously connected to neurological diseases (UBE2K, FRMD4B, the HLA gene complex)." (PMID 32699239, 2020).
FRMD4B also shares sentences with these, for which no sentence is quoted: amyloidosis diseases (1 paper); autoimmune pancreatitis (1); diabetes (1); glioma (1); gout (1); heart disease (1); Insulin resistance (1); multiple sclerosis (1); thalassemia (1); tumor (1).